Y_RNA (Y RNA )
Gene: Miscellaneous RNA gene on chromosome 10 (60,081,741 to 60,081,854, forward strand). Ensembl gene ENSG00000202190.
Homologues: Orthologues: chimpanzee Y_RNA (97% identical), macaque Y_RNA (89% identical). Paralogues in human: Y_RNA (82% identical), RNY1 (82% identical), Y_RNA (81% identical), Y_RNA (80% identical), RNY1P11 (79% identical), Y_RNA (79% identical), Y_RNA (78% identical), RNY1P10 (77% identical), Y_RNA (77% identical), RNY1P12 (76% identical), RNY1P8 (76% identical), Y_RNA (76% identical), and 93 more.